WDR4 (WDR4 tRNA N7-guanosine methyltransferase non-catalytic subunit)
Description:
Non-catalytic component of the METTL1-WDR4 methyltransferase complex required for the formation of N(7)-methylguanine in a subset of RNA species, such as tRNAs, mRNAs and microRNAs (miRNAs). In the METTL1-WDR4 methyltransferase complex, WDR4 acts as a scaffold for tRNA-binding. Required for the formation of N(7)- methylguanine at position 46 (m7G46) in a large subset of tRNAs that contain the 5'-RAGGU-3' motif within the variable loop. M7G46 interacts with C13-G22 in the D-loop to stabilize tRNA tertiary structure and protect tRNAs from decay. Also required for the formation of N(7)-methylguanine at internal sites in a subset of mRNAs. Also required for methylation of a specific subset of miRNAs, such as let-7. Independently of METTL1, also plays a role in genome stability: localizes at the DNA replication site and regulates endonucleolytic activities of FEN1.
Synonyms: hWH; TRM82; TRMT82; Wuho; GAMOS6; MIGSB
Tractability: Small molecule: a structure with a bound ligand is known. PROTAC: ubiquitination databases record sites on it; its protein half-life has been measured.
Gene: Protein-coding gene on chromosome 21 (42,843,013 to 42,879,582, reverse strand). Ensembl gene ENSG00000160193.
Subcellular location: Nucleus; Chromosome
Subcellular location (Human Protein Atlas): Nucleoplasm; Cytosol
Pathways (Reactome):
Metabolism of RNA: tRNA modification in the nucleus and cytosol
Gene Ontology:
Molecular function: enzyme activator activity; protein binding
Biological process: tRNA (guanine-N7)-methylation; tRNA modification; RNA (guanine-N7)-methylation
Cellular component: chromosome; nucleoplasm; nucleus; tRNA (m7G46) methyltransferase complex; tRNA methyltransferase complex; cytosol
Genetic constraint (gnomAD): Loss-of-function variants: 48 observed, 45.19 expected, observed/expected ratio (o/e) 1.06, 90% interval 0.84 to 1.35. The upper end of that interval is the gene's LOEUF score, 1.35, which puts it in group 5 of 6, group 1 being the genes least tolerant of losing a copy. Missense variants: 606 observed, 535.28 expected, observed/expected ratio (o/e) 1.13, 90% interval 1.06 to 1.21. Synonymous variants: 268 observed, 225.24 expected, observed/expected ratio (o/e) 1.19, 90% interval 1.08 to 1.32.
Homologues: Orthologues: chimpanzee WDR4 (98% identical), macaque WDR4 (97% identical), rabbit WDR4 (80% identical), dog WDR4 (79% identical), pig WDR4 (78% identical), guinea pig WDR4 (77% identical), mouse Wdr4 (75% identical), rat Wdr4 (74% identical), zebrafish wdr4 (42% identical), Drosophila melanogaster wuho (26% identical), Caenorhabditis elegans wdr-4 (23% identical).
Diseases named in the same sentence as WDR4 in open-access papers:
WDR4 is named in the same sentence as 71 diseases in open-access papers, as found by Europe PMC text mining. Sharing a sentence is not in itself a finding about the gene and the disease. The quoted sentences say what the papers report.
lung carcinoma (36 papers, 2022 to 2025). "Studies have demonstrated that loss of METTL1/WDR4 impairs tRNA m7G modifications, markedly inhibiting lung cancer cell proliferation, colony formation, and invasion, as well as reducing tumorigenicity in vivo." (PMID 41562049, 2025). "In lung adenocarcinoma and squamous carcinoma, the expression levels of METTLl and WDR4 were significantly elevated compared with those in normal lung tissues, and were closely associated with poor prognosis of lung cancer patients." (PMID 40443650, 2025). "We previously identified WDR4 as a substrate adaptor of Cullin 4 ubiquitin ligase and an association of WDR4 high expression with poor prognosis of lung cancer." (PMID 37821451, 2023). "In human lung cancers, WDR4/PTPN23 axis is upregulated in lung cancer and associated with adverse prognosis." (PMID 37821451, 2023). "The elevation of METTL1 and WDR4 were reported to be related with worse prognosis of human lung cancer and intrahepatic cholangiocarcinoma negatively associated with patient." (PMID 36118897, 2022). "Studies have shown that METTL1/WDR4 exhibits high expression levels in lung cancer tissues and that the loss of m7G tRNA modification impairs cell proliferation, colony formation, and cell invasiveness, ultimately reducing the tumorigenic potential of cancer cells both in vitro and in vivo." (PMID 38281298, 2024). "The upregulated expression levels of METTL1 and/or WDR4 and their association with prognosis were observed in multiple types of cancer, including lung cancer, esophageal squamous cell carcinoma (ESCC), intrahepatic cholangiocarcinoma (ICC), hepatocellular carcinoma (HCC), and glioma." (PMID 36733406, 2023). "Thus, our data indicate the existence and hyperactivation of WDR4/PTPN23 axis in human lung cancer and the association of this axis with adverse prognosis." (PMID 37821451, 2023). "Clinically, WDR4/PTPN23 axis is hyperactivated in lung cancer and associated with poor prognosis." (PMID 37821451, 2023). "It had been demonstrated experimentally that METTL1/WDR4 can regulate the development of cancer through tRNA modification of m7G methylation in intrahepatic cholangiocarcinoma, lung cancer and nasopharyngeal carcinoma." (PMID 38987843, 2024). "Clinically, PTPN23 is downregulated in lung cancer and its low expression correlates with WDR4 high expression and poor prognosis." (PMID 37821451, 2023). "WDR4 is highly expressed in lung cancer and promotes lung cancer progression and metastasis by targeting PML tumor suppressor for ubiquitination." (PMID 37821451, 2023). "To enhance our understanding of the mechanistic basis of tumor-promoting functions of WDR4-based Cul4 ubiquitin ligase, we aimed to identify its substrates in lung cancer cells using an unbiased approach." (PMID 37821451, 2023). "Through m7G alteration of tRNA or miRNA, the METTL1/WDR4 complex influences the course of several malignancies, such as liver cancer, lung cancer, and colon cancer." (PMID 36816047, 2023). "Further investigation unveiled that METTL1/WDR4 accelerated lung cancer cell proliferation and migration by enhancing tRNA m7G modification and oncogenic mRNA translation, particularly CCND3 and CCNE1, the cell-cycle regulators." (PMID 36733406, 2023). "In lung cancer, WDR4 degrades PML through the ubiquitination pathway and upregulates its downstream CD73, urokinase plasminogen activator receptor (uPAR) and serum amyloid A2 (SAA2) via HIF-1." (PMID 37710294, 2023). "METTL1 and WDR4 were found to be up-regulated in lung cancer tissues which promoted tumor cell proliferation and migration." (PMID 37710294, 2023). "Another study showed high METTL1 and WDR4 expression levels in lung cancer, facilitating m7G tRNA modification, altering mRNA translation, and boosting lung cancer development and invasion." (PMID 35982949, 2022). "Their findings uncovered the oncogenic role of METTL1/WDR4-mediated m7G tRNA modification in lung cancer." (PMID 36353111, 2022).
lung carcinoma (continued). "And m7G tRNA modifications and m7G codon usage mediated by promote METTL1/WDR4 oncogenic mRNA translation to facilitate lung cancer progression." (PMID 36396627, 2022). "METTL1/WDR4 also catalyzed m7G modification at let-7 miRNA to promoted the tumor suppressor miRNA processing from primary to precursor miRNA in lung cancer." (PMID 36396627, 2022). "WDR4 combined with METTL1 as m7G methyltransferase complex components, and it had been reported that depletion of METTL1 and WDR4 resulted in decreased lung cancer cell progression." (PMID 36761423, 2022). "The m7G methyltransferase METTL1 and WDR4 complex is significantly elevated in lung cancer, which can promote lung cancer cell growth and invasion and negatively correlate with patient prognosis." (PMID 36553648, 2022). "Furthermore, in EGFR-mutant lung cancer, combining WDR4 inhibitors with EGFR TKIs has shown potential in overcoming resistance." (PMID 40570022, 2025). "Furthermore, in lung cancer, METTL1/WDR4 deletion leads to impaired tRNA m7G modification, which affects lung cancer cell proliferation and tumourigenesis." (PMID 38572667, 2024). "Furthermore, Wang and colleagues noted that the aberrant expression and release of SAA2 regulated by WDR4/PML promotes lung cancer progression by increasing intertumoral Tregs and M2-like macrophages while reducing CD8+ T cell infiltration." (PMID 39457484, 2024). "In contrast, METTL1/WDR4-mediated m7G-modified microRNAs suppressed the progression of lung cancer." (PMID 37283791, 2023). "Next, we investigated the clinical relevance of WDR4/PTPN23 axis in lung cancer." (PMID 37821451, 2023). "METTL1 or WDR4 expression dysregulation has been detected in many tumors, including bladder cancer, head and neck squamous cell carcinoma, hepatocellular carcinoma, and lung cancer 27-30." (PMID 37283791, 2023). "Furthermore, the WDR4/PML axis is also overactive in lung cancer and promotes tumor progression in the immunosuppressive and pre-metastatic microenvironment." (PMID 36226166, 2022). "Moreover, METTL1 or WDR4 depletion inhibited proliferation and invasion, as well as in vivo tumor growth of lung cancer cells." (PMID 36353111, 2022). "Moreover, one study demonstrated that METTL1 and WDR4 were upregulated in lung cancer samples and vital for the progression." (PMID 36091687, 2022). "In lung cancer, components of the tRNA m7G methyltransferase complex, METTL1 and WDR4, are significantly upregulated and correlate with poor patient prognosis." (PMID 41562049, 2025). "WDR4 can also act as an adaptor and mediate the ubiquitination-mediated degradation of the tumor suppressor gene PML, thus promoting the progression of lung cancer." (PMID 37783676, 2023). "The WD repeat domain 4 (WDR4) complex and methyltransferase-like 1 (METTL1) complex either enhanced or impeded the processes of several malignancies, including squamous cell carcinoma and lung cancer." (PMID 40658715, 2025). "The m7G regulatory factors methyltransferase 1 (METTL1) and WD Repeat Domain 4 (WDR4) participate in the regulation of various cancer types, including HNSCC, liver cancer, bladder cancer, and lung cancer, by changing the m7G modification levels of miRNAs and tRNAs 18,19." (PMID 39440068, 2024). "In addition, WDR4 can act as a ubiquitinated substrate adaptor molecule and mediate the degradation of PML by ubiquitination to promote lung cancer progression." (PMID 37783676, 2023). "Immunohistochemistry (IHC) analysis of 119 human lung cancer tissues and 62 adjacent non-tumor lung tissues revealed that WDR4 expression was elevated in tumor tissues compared with non-tumor tissues, consistent with our previous finding." (PMID 37821451, 2023). "Additionally, in lung cancer, m7G tRNA modifications mediated by METTL1/WDR4 were found to play a crucial role in regulation of mRNA translation process and cancer progression." (PMID 36545327, 2022).
lung carcinoma (continued). "Ma's group found that both WDR4 and METTL1 were significantly upregulated in human lung cancer." (PMID 36186903, 2022). "A study of WDR4 uncovered that knockdown of WDR4 could restrain the aggressiveness of NSCLC cells, demonstrating that WDR4 may have tumorigenic function in lung cancer." (PMID 36091687, 2022). "Impaired m7G tRNA modification in the absence of METTL1/WDR4 results in decreased proliferation, colony formation, cell invasion, and tumorigenicity of lung cancer cells." (PMID 36553648, 2022). "Furthermore, WDR4 negatively regulates PML expression to enhance lung cancer development by creating a pro-metastatic and immunosuppressive status, which may be helpful for potential future treatments in lung cancer patients." (PMID 39440054, 2024). "Moreover, the expression levels of METTL1 and WDR4 were also significantly upregulated in lung cancer tissues, and METTL1-mediated m7G tRNA modifications can regulate the mRNA translation to promote the proliferation and invasion of lung cancer, revealing m7G modification as a key oncogenic factor." (PMID 37158958, 2023). "Multivariate Cox regression analysis revealed that higher WDR4 expression and lower PTPN23 expression were independent poor prognostic factors in lung cancer, irrespective of other poor prognostic factor, such as the N stage." (PMID 37821451, 2023). "In lung cancer cases, METTL1 and WDR4 were both remarkably raised and had a negative correlation with invalids’ prognosis." (PMID 36118897, 2022).
hepatocellular carcinoma (26 papers, 2021 to 2025). A malignant tumor that arises from hepatocytes. "The levels of m7G tRNA methyltransferase complex components (methyltransferase-like protein-1 and WD repeat domain 4 (WDR4)) are elevated in hepatocellular carcinoma and associated with a poor clinical outcome." (PMID 37495112, 2023). "The expression levels of METTL1 and WDR4 are elevated in hepatocellular carcinoma (HCC) and are associated with advanced tumor stage and poor patient survival." (PMID 36333719, 2022). "Previous studies also showed an overexpression of WDR4 in head and neck squamous cell carcinoma 28, hepatocellular carcinoma 29, intrahepatic cholangiocarcinoma 46, and so on, indicating that WDR4 serves as an oncogene for several cancers." (PMID 37283791, 2023). "WDR4 plays a crucial role in promoting the proliferation of hepatocellular carcinoma by mediating m7G methylation." (PMID 37396662, 2023). "In hepatocellular carcinoma, WDR4 interacts with the translation initiation factor EIF2A to promote the translation of CCNB1 and thus promote proliferation, metastasis and sorafenib resistance." (PMID 37783676, 2023). "WDR4 has a wide range of effects on the cell cycle and the immune infiltration of hepatocellular carcinoma cells." (PMID 37035153, 2023). "METTL1 and WDR4 are upregulated in hepatocellular carcinoma (HCC) and intrahepatic cholangiocarcinoma (ICC), related with poor prognosis." (PMID 36092891, 2022). "WDR4 is crucially involved in promoting the proliferation of hepatocellular carcinoma by mediating m7G methylation." (PMID 36473947, 2022). "It has been shown that the oncogenic function of METTLl can promote tumor cell proliferation and migration by inhibiting the PTEN-related signaling pathway, and that inhibition of METTL1/WDR4 activity reduces m7G tRNA modification and slows down the progression of hepatocellular carcinoma." (PMID 40443650, 2025). "Likewise, WDR4 also reduced the sensitivity of hepatocellular carcinoma cells to sorafenib by enhancing the translation of CCNB1 and the conversion of EMT." (PMID 37710294, 2023). "In our research we also found that METTL1 and WDR4 expression was upregulated in hepatocellular carcinoma tissues and correlated with reduced survival time, and also found that high METTL1 and WDR4 expression was distinctively and negatively relevant with the level of NK cell infiltration." (PMID 36389726, 2022). "Upregulated WDR4 expression increases m7G methylation levels in hepatocellular carcinoma." (PMID 36468039, 2022). "The m7G tRNA modification and the expression of its methyltransferase complex components (METTL1 and WDR4) were significantly elevated in hepatocellular carcinoma (HCC)." (PMID 39723662, 2025). "According to previous research, the expression of WDR4 transcripts was obviously upregulated in hepatocellular carcinoma (HCC), along with increasing levels of m7G methylation." (PMID 37283791, 2023). "Xia and colleagues substantiated the upregulated WDR4 in hepatocellular carcinoma (HCC), accompanied by increased m7G methylation levels." (PMID 36186903, 2022). "Accumulating evidence have verified that WDR4 expression increased the m7G methylation level in tumors, promoting tumor cell proliferation and progression, such as in hepatocellular carcinoma (HCC) and neck squamous cell carcinoma." (PMID 36353111, 2022). "MYC-targeted WDR4 promoted proliferation, metastasis and sorafenib resistance by inducing CCNB1 translation in hepatocellular carcinoma." (PMID 40303931, 2025). "In hepatocellular carcinoma, METTL1/WDR4-mediated m7G tRNA modification significantly promotes the translation of cyclin A2, EGFR, and VEGFA, promoting the spread and metastasis of hepatocellular carcinoma cells." (PMID 39019857, 2024). "In hepatocellular carcinoma, the METTL1/WDR4 complex promoted the translation of EGFR pathway genes via modulating m7G tRNA modification, which decreased the tumor’s susceptibility to Lenvatinib." (PMID 37710294, 2023).
hepatocellular carcinoma (continued). "WDR4 interacts with EIF2A to promote the translation of CCNB1, thereby promoting the proliferation, metastasis and sorafenib resistance of hepatocellular carcinoma cells." (PMID 37783676, 2023). "WDR4 promotes tumor cells metastasis and resistance to sorafenib via epithelial-mesenchymal transition (EMT), thereby promoting the proliferation of hepatocellular carcinoma cells." (PMID 36389726, 2022). "Therefore, in the present study, we first used The Cancer Genome Atlas-Liver Hepatocellular Carcinoma (TCGA-LIHC) dataset and clinical data to assess WDR4 transcript levels in HCC and their impact on HCC patient prognosis." (PMID 34244479, 2021). "It was shown that m7G tRNA modification and its methyltransferases METTL1, WDR4 and WBSCR22 were significantly elevated in HCC and promoted the proliferation, migration and invasion of hepatocellular carcinoma cells." (PMID 37710294, 2023). "However, there is no doubt that METTL1, WDR4 and WBSCR22 are potential targets for the future treatment of hepatocellular carcinoma." (PMID 37710294, 2023).